F2 (coagulation factor II, thrombin)
Description:
Thrombin, which cleaves bonds after Arg and Lys, converts fibrinogen to fibrin and activates factors V, VII, VIII, XIII, and, in complex with thrombomodulin, protein C. Functions in blood homeostasis, inflammation and wound healing. Activates coagulation factor XI (F11); activation is promoted by the contact with negatively charged surfaces. Triggers the production of pro-inflammatory cytokines, such as MCP-1/CCL2 and IL8/CXCL8, in endothelial cells.
Synonyms: PT; RPRGL2; THPH1
Tractability: Small molecule: an approved drug acts on it; a structure with a bound ligand is known; a high-quality ligand is known; it has a high-quality binding pocket; it belongs to a druggable protein family. Antibody: a drug acting on it is in phase 2 or 3 trials; its Gene Ontology location is reachable by antibodies, with high confidence; UniProt places it where antibodies can reach, with medium confidence; UniProt predicts a signal peptide or a membrane-spanning region. PROTAC: its protein half-life has been measured; a small molecule that binds it is known. Other modalities: an approved drug acts on it.
Target class: Serine protease; Enzyme; Serine protease PA clan; Serine protease S1A subfamily; Protease
Chemical probes: PD080855, PD081428, PD081865, PD082903
Safety:
Unwanted effects reported when the protein is acted on. In parentheses: how it was acted on, where the effect was seen, and who reports it.
hemorrhagic events (inhibition; cardiovascular system; source: Urban et al. (2012))
deep vein thrombosis (source: ClinPGx)
Impaired recruitment , Population trajectory (source: AOP-Wiki)
Gene: Protein-coding gene on chromosome 11 (46,719,166 to 46,739,822, forward strand). Ensembl gene ENSG00000180210.
Subcellular location: Secreted, extracellular space
Pathways (Reactome):
Hemostasis: Amplification and propagation of coagulation cascade; Cell surface interactions at the vascular wall; Fibrin formation; Initiation of coagulation cascade; Platelet Aggregation (Plug Formation); Regulation of clotting cascade; Thrombin signalling through proteinase activated receptors (PARs)
Metabolism of proteins: Gamma-carboxylation of protein precursors; Regulation of Insulin-like Growth Factor (IGF) transport and uptake by Insulin-like Growth Factor Binding Proteins (IGFBPs); Removal of aminoterminal propeptides from gamma-carboxylated proteins; Transport of gamma-carboxylated protein precursors from the endoplasmic reticulum to the Golgi apparatus
Disease: Defective F8 cleavage by thrombin; Defective factor XII causes hereditary angioedema; Dengue Virus-Host Interactions
Signal Transduction: G alpha (q) signalling events; Peptide ligand-binding receptors
Immune System: Regulation of Complement cascade
Gene Ontology:
Molecular function: heparin binding; lipopolysaccharide binding; protein binding; receptor ligand activity; serine-type endopeptidase activity; signaling receptor binding; thrombospondin receptor activity; growth factor activity; calcium ion binding; endopeptidase activity; peptidase activity
Biological process: antimicrobial humoral immune response mediated by antimicrobial peptide; cell surface receptor signaling pathway; fibrinolysis; negative regulation of astrocyte differentiation; negative regulation of blood coagulation; negative regulation of cytokine production involved in inflammatory response; negative regulation of proteolysis; neutrophil-mediated killing of gram-negative bacterium; platelet activation; positive regulation of blood coagulation; positive regulation of collagen biosynthetic process; positive regulation of phospholipase C-activating G protein-coupled receptor signaling pathway; positive regulation of protein localization to nucleus; positive regulation of reactive oxygen species metabolic process; positive regulation of release of sequestered calcium ion into cytosol; regulation of cytosolic calcium ion concentration; response to wounding; thrombin-activated receptor signaling pathway; blood coagulation; negative regulation of fibrinolysis; negative regulation of platelet activation; positive regulation of receptor signaling pathway via JAK-STAT; proteolysis; regulation of blood coagulation; G protein-coupled receptor signaling pathway; and 1 more
Cellular component: blood microparticle; external side of plasma membrane; extracellular exosome; extracellular matrix; extracellular region; endoplasmic reticulum lumen; Golgi lumen; plasma membrane
Genetic constraint (gnomAD): Loss-of-function variants: 35 observed, 84.03 expected, observed/expected ratio (o/e) 0.42, 90% interval 0.32 to 0.55. The upper end of that interval is the gene's LOEUF score, 0.55, which puts it in group 2 of 6, group 1 being the genes least tolerant of losing a copy. Missense variants: 630 observed, 851.55 expected, observed/expected ratio (o/e) 0.74, 90% interval 0.69 to 0.79. Synonymous variants: 296 observed, 329.98 expected, observed/expected ratio (o/e) 0.9, 90% interval 0.81 to 0.99.
Gene-disease validity (ClinGen):
ClinGen rates the evidence that F2 causes each of these diseases.
congenital prothrombin deficiency (autosomal recessive): Definitive. Congenital factor II deficiency is an inherited bleeding disorder due to reduced activity of factor II (FII, prothrombin) and characterized by mucocutaneous bleeding symptoms.
thrombophilia due to thrombin defect (autosomal dominant): Definitive. The formation of a blood clot (thrombus) in the lumen of a vein.
Homologues: Orthologues: chimpanzee F2 (99% identical), macaque F2 (87% identical), dog F2 (84% identical), pig F2 (83% identical), mouse F2 (81% identical), rat F2 (79% identical), guinea pig F2 (75% identical). Paralogues in human: PAMR1 (20% identical).
Diseases named in the same sentence as F2 in open-access papers:
F2 is named in the same sentence as 104 diseases in open-access papers, as found by Europe PMC text mining. Sharing a sentence is not in itself a finding about the gene and the disease. The quoted sentences say what the papers report.
COVID-19 (30 papers, 2020 to 2025). A disease caused by infection with severe acute respiratory syndrome coronavirus 2. "The key targets in the PPI network also present in the “Coronavirus disease - COVID-19” pathway included IL6, MAPK1, JUN, F2, and TNF." (PMID 38050310, 2023). "Through network analysis, it was found that the core targets of GGQL in the treatment of COVID-19 comorbid with DM include AR, GSK3B, DPP4, F2, NOS3, and so on." (PMID 37933071, 2023).
thrombosis (21 papers, 2011 to 2025). "For example, it is well known that polymorphic variants at the F2 gene (coagulation factor II or thrombin) are associated with thrombosis as well as with changes in the level of HDL-C." (PMID 35203469, 2022).
Hypertension (4 papers, 2015 to 2025). The presence of chronic increased pressure in the systemic arterial system. "The upregulated circulating proteins in PE+ (AMBP, VTN, CLU, F2, PZP, APCS, and HBB) are involved in blood pressure regulation, extracellular matrix dynamics, and immune system function, highlighting the pathogenesis of this hypertensive disorder in the context of inflammation and immune defense." (PMID 40673030, 2025).
venous thromboembolism (4 papers, 2011 to 2023). Occlusion of the lumen of a vein by a thrombus that has migrated from a distal site via the blood stream. "While initially the drug target F2 (coagulation factor II, thrombin) for venous thromboembolism (VTE) ranked only in the top 2%, it moved up to the top 1% regardless of the network used for diffusion at r = 0.6 (top 0.9%, 0.6%, and 0.7% for STRING, CoXRNAseq, and FAVA, respectively)." (PMID 37492104, 2023).
viral infection (4 papers, 2005 to 2022). "In particular, vWF, HRG, PROS1, GC, F2, FGA, and FGB proteins, which are responsible for the expansion of vessels and new vessel formation, modulate blood coagulation and mitigate against vasoconstriction and coagulation caused by virus infection." (PMID 35401544, 2022).
autoimmune disease (2 papers, 2021 to 2024). A disorder resulting from loss of function or tissue destruction of an organ or multiple organs, arising from humoral or cellular immune responses of the individual to their own tissue constituents. "The non-CHD indications of clinically used drugs included dyslipidemias (PPARA), type 2 diabetes (PPARG and NDUFA13), autoimmune diseases (TNF), neoplasms (RAF1 and PSMA5), circulatory disorders (ABCA1, PLG, ITGB3, and F2), and alcohol-dependency (ALDH2)." (PMID 34675202, 2021).
bladder cancer (2 papers, 2023). "Through PPI network analysis, we identified RPL8 and F2 as therapeutic drug targets that were significantly overexpressed in bladder cancer." (PMID 37147328, 2023).
chronic kidney disease (2 papers, 2019 to 2022). Impairment of the renal function secondary to chronic kidney damage persisting for three or more months. "This study shows that cell proliferation, differentiation, apoptosis, migration (SRC, HRAS, HSP90AA1, CDK2), and ameliorating chronic kidney disease (MAPK14, F2, LCK, MMP9) appear to play important roles in the therapeutic effect of SQW." (PMID 31275142, 2019).
co-infection (2 papers, 2021 to 2024). "Interestingly, with the exception of F2, proteins upregulated by M. bovis alone were downregulated by the addition of IDV as a co-infection." (PMID 38543727, 2024).
ovarian carcinoma (2 papers, 2021 to 2022). A malignant neoplasm originating from the surface ovarian epithelium. "Coagulation factor II (F2) is found to be overexpressed in various epithelial neoplasms including ovarian cancer; F2 receptor, also known as PAR1, has been provided to be differentially expressed in ovarian cancer tissue." (PMID 35646648, 2022).
psoriasis (2 papers, 2022 to 2025). An autoimmune condition characterized by red, well-delineated plaques with silvery scales that are usually on the extensor surfaces and scalp. "A few DEPs, such as SERPINC1, SERPINF2, F2, PLXDC2, and TYMP, were also involved in regulating blood coagulation and angiogenesis, which plays an essential role in the pathogenesis and maintenance of psoriasis." (PMID 36483564, 2022).
allergic rhinitis (1 paper, 2024). Inflammation of the nasal mucous membranes caused by an IgE-mediated response to external allergens. "Furthermore, the MCODE plugin was employed to pinpoint 14 genes (Cyba, Nfkbia, Fos, Mpo, Il6, Il1b, Sele, Vcam1, F2, Tlr4, Alb, Egr1, Smad3, and Ptgs2) forming a primary cluster, potentially representing a crucial regulatory network for berberine in treating allergic rhinitis." (PMID 38796469, 2024).
gastric cancer (1 paper, 2020). A primary or metastatic malignant neoplasm involving the stomach. "F2, which encodes the coagulation factor II (also known as thrombin), is a pro-inflammatory and pro-coagulant molecule that is elevated in various cancers, including breast and gastric cancers." (PMID 32226313, 2020).
mammary tumours (1 paper, 2018). "The top upstream regulators in malignant mammary tumours were secreted phosphoprotein (SPP1) and coagulation factor II (F2)." (PMID 30517191, 2018).
tongue cancer (1 paper, 2025). A malignant neoplasm affecting the tongue. "Red rectangles represent the hit genes involved in the treatment of tongue cancer (TERT, Bcl-2, CDK4/6, CDK2, VEGF, ER, RXR,c-KIT, MET, FGFR, PPAR8, PFFP, MMPs, CDK4, AR, F2, IGFR)." (PMID 39863836, 2025).
cancer (15 papers, 2007 to 2025). A tumor composed of atypical neoplastic, often pleomorphic cells that invade other tissues. "Although the binding of Zt/f2 results in RON phosphorylation, it subsequently causes RON internalization leading to diminished RON expression in cancer cells." (PMID 21749705, 2011). "PML, C3, TXN, KRT6C, F2, PTK2, TNF, which could enable HIF-mediated inflammatory response during cancer development." (PMID 36845724, 2023).
infection (10 papers, 2005 to 2024). The state of being infected such as from the introduction of a foreign agent such as serum, vaccine, antigenic substance or organism. "In order to identify host proteins binding to PB1-F2 during infection, we reconstituted this virus, VN/1203 ΔF2, by infecting HEK 293T cells (293T cells) expressing N-terminally Flag-tagged PB1-F2 of VN/1203." (PMID 29563290, 2018).
F2 also shares sentences with these, for which no sentence is quoted: tumor (15 papers); coagulopathy (8); thrombophilia (8); Thrombocytopenia (7); lupus (6); Sepsis (6); antiphospholipid syndrome (4); Cirrhosis (4); diabetes (4); liver fibrosis (4); Arterial thrombosis (3); lung carcinoma (3); Stroke (3); acute kidney injury (2); chronic obstructive pulmonary disease (2); colon cancer (2); End Stage Liver Disease (2); hemophagocytic lymphohistiocytosis (2); Hepatitis (2); hepatitis B (2); hyperhomocysteinemia (2); influenza (2); liver cirrhosis (2); myocardial infarction (2); preeclampsia (2); respiratory disease (2); achondroplasia (1); Acromicric dysplasia (1); active tuberculosis (1); acute respiratory distress syndrome (1).
A further 57 diseases each share a sentence with F2 in 1 paper.